NGF (nerve growth factor)
Diseases named in the same sentence as NGF in open-access papers (continued):
Sharing a sentence is not in itself a finding about the gene and the disease.
osteosarcoma (continued). "The fact that MEK inhibitors also suppress NGF-induced ERK phosphorylation suggests that MEK-dependent ERK activation mediates the NGF-promoted synthesis of MMP-2 and osteosarcoma cell motility." (PMID 38816365, 2024). "In the current study, we explored the involvement of MEK/ERK signaling in moderating the NGF-induced promotion of MMP-2-mediated wound healing, as well as the migratory and invasion abilities of osteosarcoma cells." (PMID 38816365, 2024). "We also observed high expression levels of NGF and MMP-2 proteins in late-stage tumor samples in an osteosarcoma tissue array." (PMID 38816365, 2024). "In our exploration of the impact of NGF on cell motility in osteosarcoma cell lines (143B and MG63), it was observed that NGF treatment led to dose-dependent improvements in wound healing, migration, and invasion abilities." (PMID 38816365, 2024). "In the current study, we obtained in vitro and in vivo evidence of NGF facilitating VCAM-1-dependent monocyte adhesion and M2 macrophage polarization in the osteosarcoma microenvironment." (PMID 39247831, 2024). "In the current study, NGF promoted the phosphorylation of MEK and ERK, while pharmacological inhibitors and siRNA targeting MEK and ERK inhibited NGF-induced MMP-2 expression and the migration of osteosarcoma cells." (PMID 38816365, 2024). "MEK and ERK inhibition significantly attenuated the effects of NGF in promoting MMP-2 mRNA expression and migratory and invasion activity in osteosarcoma cells." (PMID 38816365, 2024). "Pre-treating osteosarcoma cells with MEK and ERK inhibitors or their respective siRNAs reversed the effects of NGF in repressing miR-92a-1-5p expression." (PMID 38816365, 2024). "Treating osteosarcoma cells with MEK and ERK inhibitors or siRNA was shown to reverse the inhibitory effect of NGF on miR-92a-1-5p expression." (PMID 38816365, 2024). "In summary, this study confirmed that NGF suppresses the synthesis of miR-92a-1-5p via the MEK/ERK signaling cascade, thereby promoting the MMP-2-dependent migration of osteosarcoma cells." (PMID 38816365, 2024). "In cellular experiments using human osteosarcoma cells (143B and MG63), NGF upregulated MMP-2 expression and promoted wound healing, cell migration, and cell invasion." (PMID 38816365, 2024). "Treating osteosarcoma cells (143B and MG63) with NGF (100 ng/mL) revealed the significant downregulation of three miRNAs, namely miR-92a-1-5p, miR-4271, and miR-6883-5p." (PMID 38816365, 2024). "In orthotopic osteosarcoma models lacking fusions, pharmacologic TrkA blockade dampened NGF-induced MMP-2 programs and reduced metastatic spread, consistent with the NGF/MMP axis observed in patient and cell-based datasets." (PMID 41567220, 2025). "Although these findings require clinical corroboration, they nominate TRK blockade as a strategy to disable NGF-driven stromal remodeling and dissemination in osteosarcoma irrespective of fusion status." (PMID 41567220, 2025). "Beyond canonical fusion-driven settings, preclinical work indicates that NGF–TrkA signaling can be pharmacologically suppressed to blunt prometastatic programmes even in fusion-negative osteosarcoma." (PMID 41567220, 2025). "In this review, we summarized NGF/BDNF expression and receptor activity in osteosarcoma and conducted a translational, efficacy− and safety−oriented appraisal of tissue/biofluid biomarker readouts and drugging opportunities targeting neurotrophin and co−regulatory neural circuits." (PMID 41383615, 2025). "Among these, nerve growth factor (NGF) binding to tropomyosin receptor kinase A (TrkA) and brain-derived neurotrophic factor (BDNF) binding to TrkB represent two conserved signaling axes with direct relevance to osteosarcoma biology and its immune milieu." (PMID 41567220, 2025). "Mechanistic map of NGF/TrkA and BDNF/TrkB effects on immune and stromal components in osteosarcoma." (PMID 41567220, 2025).
osteosarcoma (continued). "We also observed a positive correlation between NGF and MMP-2 expression in osteosarcoma tissue." (PMID 38816365, 2024). "In osteosarcoma samples from the Genomic Data Commons data portal, we detected higher levels of NGF and M2 macrophage markers, but not M1 macrophage markers." (PMID 39247831, 2024). "Targeting NGF expression is a promising approach to the development of novel treatments for metastatic osteosarcoma." (PMID 38816365, 2024). "We determined that NGF stimulation led to MEK and ERK phosphorylation in osteosarcoma cells." (PMID 38816365, 2024). "In the current study, we confirmed that NGF promotes the migration of osteosarcoma cells by mediating the production of MMP-2, rather than other MMPs." (PMID 38816365, 2024). "Osteosarcoma cells transfected with VCAM-1 siRNA were shown to antagonize VCAM-1 expression and moderate NGF-induced monocyte adhesion, which indicates that NGF augments VCAM-1-dependent monocyte adhesion to osteosarcoma." (PMID 39247831, 2024). "Recently, advances in cancer neuroscience have highlighted neurotrophins—nerve growth factor (NGF) and brain−derived neurotrophic factor (BDNF)—and their Trk/p75NTR receptors as modulators of tumor behavior and immune tone, offering a new strategy to recondition the osteosarcoma microenvironment." (PMID 41383615, 2025). "When executed with these principles, testing of NGF/BDNF−directed agents alone and in combinations designed to normalize vascular and cytokine tone should determine whether neuromodulatory strategies can convert immunologically quiescent osteosarcoma into a treatment−responsive state." (PMID 41383615, 2025).
adrenal pheochromocytoma (10 papers, 2014 to 2025). "The PC12 cell lines (the adrenal gland pheochromocytoma) were used as models for neurite outgrowths, and NGF was used as the positive control to cease proliferation and transform to generate apparent neurites with neuronal markers." (PMID 39692936, 2024). "NGF has been reported to enhance the neurite extension in rat adrenal pheochromocytoma (PC12) cells and sensory neurons via TrkA receptors." (PMID 33466524, 2021). "To explore the role of IL-20 in axonal regeneration, we analyzed the expression of IL-20 and its receptors in PC-12 cells, a rat adrenal pheochromocytoma cell line that responds reversibly to nerve growth factor (NGF) by induction of the neuronal phenotype." (PMID 32408881, 2020). "PC12 is derived from rat adrenal pheochromocytoma that are notably nerve growth factor (NGF) receptive." (PMID 32033400, 2020). "The PC12 cell line was established from a transplantable rat adrenal pheochromocytoma based on its response to nerve growth factor (NGF)." (PMID 25383141, 2014). "The PC12 cell line, derived from rat adrenal medullary pheochromocytoma, has been used to study neuronal plasticity because it differentiates into neuron-like cells and promotes neurite outgrowth in response to drugs such as nerve growth factor (NGF)." (PMID 40427418, 2025). "Among them, the rat adrenal pheochromocytoma PC12 cell line is known to synthesize and store DA and sometimes norepinephrine (NA), and is induced to differentiate into a mature sympathetic neuron-like phenotype by the nerve growth factor (NGF)." (PMID 37376027, 2023). "mPRβ mRNA was drastically increased during NGF-induced neurogenesis in PC12, a rat adrenal pheochromocytoma cell line, whereas the expression of other progesterone receptors such as mPRα, Progesterone Receptor (PR), and PGRMC-1 did not exhibit the same expression profile." (PMID 28701790, 2017). "The rat adrenal pheochromocytoma (PC12) cell line, which represents a well-established model system for the investigation of neuronal differentiation and function, was used to elucidate the effects of ILA on neuritogenesis, following nerve growth factor (NGF) induction." (PMID 32178456, 2020).
allergic rhinitis (10 papers, 2005 to 2023). Inflammation of the nasal mucous membranes caused by an IgE-mediated response to external allergens. "The first gene on the list, NGF (nerve growth factor), is related to cytoskeleton dynamics, but is also known to be associated with allergic rhinitis." (PMID 37371794, 2023). "Upon allergen provocation, neurotrophins (BDNF, NGF) showed enhanced expression in nasal mucosa and nasal lavage that correlated with symptom severity in allergic rhinitis adult patients." (PMID 32596360, 2020). "The excessive production of NGF found in past studies of allergic rhinitis patients is again of interest, because one of our past DF clinical trials provided tangible symptomatic benefits against this condition." (PMID 22548124, 2012). "In patients with allergic rhinitis, levels of NGF in NAL were increased after allergen provocation compared with control subjects." (PMID 16002371, 2005). "In addition, immune cells such as eosinophils, mast cells and basophils can synthesize large amounts of NGF and further release, thus forming a positive feedback immune response, aggravating the progress of allergic rhinitis." (PMID 32063751, 2020). "Overall, for the majority of measures for allergic rhinitis, ADHD, and NGF analysis, the methylphenidate and cetirizine combination produced a greater impact than did either drug individually or placebo." (PMID 27872863, 2016). "Further studies are needed to elucidate some of the interactions between the neuropeptides: SP, CGRP, and VIP and the neurotrophins NGF and BDNF and some Th1, Th2, and proinflammatory cytokines in allergic rhinitis." (PMID 23476696, 2013). "Both nasal NGF and BDNF expressions were reported to be significantly increased in allergic rhinitis patients compared to healthy controls after nasal allergen provocation." (PMID 23476696, 2013). "Concentrations of NGF, BDNF, and NT-3 increase dramatically in the respiratory epithelium during allergic rhinitis." (PMID 23476696, 2013). "Acupuncture may downregulate neurotrophins NGF and BDNF in allergic rhinitis, but evidence is currently lacking." (PMID 26339274, 2015).
colorectal cancer (10 papers, 2017 to 2026). A primary or metastatic malignant neoplasm that affects the colon or rectum. "Emerging evidence demonstrates that CSCs isolated from gastric and colorectal cancers secrete neurotrophic factors such as nerve growth factor (NGF) and brain-derived neurotrophic factor (BDNF), which promote axonal growth and sympathetic/cholinergic marker expression in peripheral neurons." (PMID 41601691, 2026). "NGF‐high CAFs promote colorectal cancer cell proliferation by activating the PI3K/AKT pathway." (PMID 41164803, 2025). "Similarly, in colorectal cancer, norepinephrine induces CAFs to secrete NGF in an ADRB2‐dependent manner." (PMID 41164803, 2025). "In addition, NGF, a neurotrophic factor, is known to be highly expressed in primary colorectal cancer tissues and promote colorectal cancer metastasis." (PMID 35163520, 2022). "Thus, the antagonists of NGF synthesis are promising in the treatment of the tumors with the high neural invasion, such as pancreas, head and neck, and colorectal cancers, but at the same time there is evidence for the possible serious cancerogenic side effects of NGF agonists and mimetics." (PMID 41562905, 2025). "In colorectal cancer, NE induces ADRB2-dependent NGF secretion from CAFs, which directly enhances colorectal cancer cell growth via the phosphatidylinositol-3-kinase/AKT pathway." (PMID 41030446, 2025). "In colorectal cancer, NE induces adrenoceptor beta 2 (ADRB2)-dependent nerve growth factor (NGF) secretion from CAFs, which in turn increases intra-tumor sympathetic innervation and NE accumulation, leading to tumor cell growth and worse prognosis." (PMID 41030446, 2025).
Insulin resistance (10 papers, 2017 to 2025). Increased resistance towards insulin, that is, diminished effectiveness of insulin in reducing blood glucose levels. "Of note, the hyperandrogenism observed in ovaries overexpressing NGF recapitulates the association between insulin resistance and hyperandrogenism in PCOS patients (up to 75% of PCOS patients have impaired insulin sensitivity)." (PMID 36768281, 2023). "Along with the positive associations of specific interleukins with insulin resistance and secretion, NGF was higher in the gestational diabetes patients and strongly linked to glucose metabolism, insulin resistance and pancreatic β cell function in Chinese pregnant women in the second trimester." (PMID 37280257, 2023). "Noteworthy, we set up and fully characterized an in vitro model of insulin resistance developed in cholinergic neurons, to study the underlying molecular events and assess candidate drug, like nerve growth factor (NGF), for counteracting the insulin-resistant state of BFCN." (PMID 29736736, 2019). "Moreover, the evidence in PCOS models suggests that increased NGF signaling in the ovaries could increase the risk of developing insulin resistance and MS in women." (PMID 36768281, 2023). "In addition to the positive associations of IL-6 and leptin with insulin resistance and secretion, NGF was higher in the GDM patients and strongly linked to glucose metabolism, insulin resistance and pancreatic β cell function in Chinese pregnant women in the second trimester." (PMID 33292292, 2020). "However, in our study, we found NGF levels were positively associated with insulin resistance, which might be ascribed to the compensatory adjustment." (PMID 33292292, 2020). "The evidence demonstrates that dysregulation of NGF signaling in the ovaries participates in the development of PCOS and altered synthesis of sex hormones, a condition linked to insulin resistance and MS in women." (PMID 36768281, 2023). "Moreover, in the second trimester, in addition to the positive associations of IL-6 and leptin with insulin resistance, NGF was closely related to glucose metabolism, insulin resistance and pancreatic β cell function and might be a protective factor in the pathological process of GDM." (PMID 33292292, 2020). "Ongoing collaborative studies are aimed at testing the in vivo potential of intranasal NGF administration on neuronal insulin resistance in AD and T2D mouse models." (PMID 29736736, 2019). "By means of these paradigms, we observed that nerve growth factor (NGF) reduces insulin resistance in vitro and in vivo." (PMID 29736736, 2019). "Noteworthy, NGF sustained the level of ChAT, a cholinergic marker affected by insulin resistance, possibly by ChAT stabilization, exerting further neuroprotective action for BFCN in AD-like neurodegeneration." (PMID 29736736, 2019). "This leads to peripheral insulin resistance and impairment of pancreatic β-cell insulin secretion, while the adipocytes elevate adipokine secretion, NGF, interleukin 6 (IL-6), IL-1, tumor necrosis factor-α (TNF-α), and monocyte chemoattractant protein-1 (MCP-1)." (PMID 37373824, 2023). "Moreover, NGF is able to stimulate the insulin pathway in control conditions and to improve insulin resistance induced by chronic high insulin in cultured cholinergic neurons." (PMID 29736736, 2019). "Based on our observation that NGF mainly ameliorates insulin resistance by IRS1 activation, we thus asked whether the effect of NGF on glucose metabolism is mediated by IRS1 in cholinergic neurons." (PMID 29736736, 2019). "Moreover, NGF could reduce insulin resistance both in vitro and in vivo by activating insulin receptor substrate 1 (IRS1)." (PMID 33292292, 2020). "Interestingly, our data indicate that NGF may counteract the detrimental effects of brain insulin resistance by acting on the IRS1 stimulation, the early, main and common effector of insulin and IGF1 receptors signalings." (PMID 29736736, 2019).
Insulin resistance (continued). "Insulin resistance and altered adipokine signaling may disrupt epithelial metabolism and tear film homeostasis, while decreased levels of neurotrophic and growth factors such as NGF and epidermal growth factor (EGF) can impair corneal nerve regeneration and epithelial healing." (PMID 41303830, 2025). "That is, when insulin resistance occurs in SCs, the expression of neurotrophic factors including CTNF, NGF, NT-3, BDNF is significantly suppressed, and the expression of myelination proteins is also decreased." (PMID 36291547, 2022). "Therefore, NGF levels are supposed to have a negative relationship with insulin resistance." (PMID 33292292, 2020).